STAT1 (signal transducer and activator of transcription 1)
Diseases named in the same sentence as STAT1 in open-access papers (continued):
Sharing a sentence is not in itself a finding about the gene and the disease.
tumor (continued). "It has been reported that tumor cell apoptosis mediated by the activation of PAR-1 is associated with tyrosine phosphorylation of JAK2 and STAT1, and translocation of STAT1 to the nucleus." (PMID 33935784, 2021). "Studies have shown that IFN-gamma can further regulate the expression of MHC-I molecules on the surface of tumor cells by activating STAT1." (PMID 34367132, 2021). "In support of this notion, anti-proliferative and pro-apoptotic effects of STAT1 in tumor cells were reported in early studies." (PMID 34830176, 2021). "The signal transducer and activator of transcription 1 (STAT1), in addition to its role as a transmitter of interferon (INF) signaling and pro-apoptotic tumor suppressor, has been associated with energy metabolism regulation." (PMID 34900673, 2021). "The anti-tumor immune response is largely driven by STAT1 and STAT2 induced type I and II IFN and downstream program-enhanced IFN." (PMID 34215720, 2021). "Elevated STAT1 increases intra-tumor CD8+ T cells, which plays a significant role in tumor inhibition by direct cytotoxicity." (PMID 33834023, 2021). "M1 microglial subtype performs an anti-tumor immune function by producing pro-inflammatory cytokines, ROS, and express signal transducer and activator of transcription 1 (STAT1)." (PMID 33917013, 2021). "Activation of the anti-proliferative STAT1 pathway by IFN-γ can lead to sensitization of tumor cells to FAS (CD95) and TRAIL resulting in apoptosis, and hindered tumor cell growth by inhibiting angiogenesis to induce a state of cellular dormancy." (PMID 34012451, 2021). "Tumor-associated macrophages produce and secret IL-10 which promotes cancer stemness via the JAK/STAT1 and NF-κB/Notch1 pathways in non-small cell lung cancer." (PMID 33834023, 2021). "Immunohistochemical staining of tumor sections clearly revealed that lentiviral delivery of shRNA specific to Stat1 is effective in suppressing Stat1 expression." (PMID 34685622, 2021). "Single cell RNA sequencing data confirm the existence of a tumor-infiltrating CXCL10+IRF1+STAT1+ M1-type TAM overexpressing antigen processing and presentation gene programs." (PMID 34220848, 2021). "We further explored immunologic signatures pathway and revealed that immunologic gene such as IL-2 and STAT1 was enriched in tumor cells." (PMID 34026600, 2021). "However, on the other hand, STAT1 deficiency studies show that STAT1 may act as a tumor suppressor." (PMID 34572789, 2021). "More and more studies of STAT1 in cancer unveil the mechanisms of tumor development and focus on the target of the immune response." (PMID 33834023, 2021). "In this study, we found that Oct4 regulates Stat1 expression, which leads to cell survival via enhanced Mcl-1 expression and promotes tumor growth in a Stat1-dependent manner." (PMID 34685622, 2021). "Several studies highlight this complex relationship between JAK/STAT1 signaling, tumor immunity, and sensitivity to immune checkpoint inhibitors in oncology." (PMID 33807608, 2021). "Traditionally, M1 subpopulations of microglial cell activation enhance the expression of STAT1, to reactivate immune response restricting tumor growth." (PMID 34504845, 2021). "The positive tumor STAT1 expression was significantly associated with higher PD-L1 expression and higher MHC class I expression, on tumor cells and also non-tumor cells." (PMID 34758826, 2021). "For instance, paracrine anti-viral RIG-I and juxtacrine NOTCH (NOTCH3-JAG1) have both been identified as contributors to therapy-resistance, which they facilitate by inducing tumor-initiating cell expansion in a STAT1-dependent fashion." (PMID 34646829, 2021).
tumor (continued). "For example, interferon-inducible protein 16 (IFI16), which is induced by STAT1, exert anti-tumor effects but protect cancer cells from being killed by chemo-drugs at the same time." (PMID 33834023, 2021). "Concordantly, both the TWIST1 and STAT1 are highly and specifically enriched in the F_3 subset which we have annotated as pro-tumor myofibroblasts." (PMID 34921160, 2021). "In this work, we adapted mathematical modelling to investigate the role of regulatory cytokines (IFN-β, JAK2) on tumour growth through the corresponding intracellular signalling networks and mutual inhibition mechanism between STAT1 and STAT3." (PMID 34631119, 2021). "In summary, combination treatment with oHSV and MEKi Trametinib enhanced virus replication mediated by down-regulation of STAT1 and PKR phosphorylation in BRAF V600E-mutated tumor cells as well as BRAF wt/KRAS-mutated tumor cells." (PMID 34578339, 2021). "We also demonstrated that the increased susceptibility of caspase-11 deficient mice to CAC was associated with decreased STAT1 activity, identifying a novel anti-tumor role for caspase-11 during CAC via its ability to provide positive enhance STAT1 activation." (PMID 33546173, 2021). "Our observation of higher expression of IFN-γ and STAT1 in Pik3cg−/− mice at the tumor site indicates a potential anti-tumor cytotoxic response." (PMID 33668795, 2021). "Confirming previous analyses, MUC1 expression was detectable in TNBC tumor cell populations, along with STAT1 and IRF1." (PMID 33495298, 2021). "IFN-γ/STAT1 signaling has tumor suppressor function and is inactive in at least one-third of all melanoma and lung adenocarcinoma cell lines in mice." (PMID 33494284, 2021). "The index tumor was found to be the most responsive to ruxolitinib, which corresponds to the high levels of STAT1/2 recorded in this tumor." (PMID 34943910, 2021). "STAT1 is also a known tumor suppressor, whereas STAT3 is a well-known oncogene that is involved in the proliferation and survival of cancer cells." (PMID 33805945, 2021). "TH1 cells can reduce proliferation and mediate dormancy in these disseminated cancer cells (DCC) via IFN-γ dependent STAT1 signaling pathway activation and anti-tumor immunity." (PMID 34012451, 2021). "The IR-induced energy deprivation of proliferating STAT1-suppressed tumor cells constitutes a potential mechanism of tumor radiosensitization." (PMID 34900673, 2021). "miR-21, a key regulator of apoptosis and tumor progression, can be overexpressed in tumor-stimulated macrophages and downregulate STAT1 and Janus kinase 2 (JAK2)." (PMID 35116035, 2021). "STAT1, which is a member of the family of signal transducers and transcription activators, corresponded to lymph node metastasis, advanced stage, tumor dedifferentiation and poor prognosis in patients with PC." (PMID 32850392, 2020). "It has been demonstrated that TNF‐α as the critical trigger along with increased activation of JAK1/STAT1 plays a crucial role in tumor cell proliferation and invasiveness." (PMID 32677756, 2020). "In PBRM1 wild-type tumors, IFNγ induces the tumor cell-autonomous expression of STAT1, IRF1 and of chemoattractive chemokines, which enhances T-cell infiltration and activation." (PMID 32358509, 2020). "Nuclear expression of STAT1 was positively correlated with poor tumor differentiation, right-sided location, and the MSI subtype." (PMID 32275681, 2020). "AA breast cancer patients also show increased expression of STAT1 (which acts as a tumor suppressor) in the early stages of tumor initiation." (PMID 32824813, 2020). "As a whole, our study revealed a novel tumor-promoting mechanism involving LINC00669/SOCS1/STAT1 regulatory network in NPC." (PMID 32831137, 2020). "Taken together, these data suggest that tumor cell-intrinsic Stat1-Ido1 expression favors immune escape and progression of human CRC." (PMID 32444775, 2020).
tumor (continued). "Tumor cells, in fact, promote the expression of miR-21 in macrophages, which inhibit STAT1, JAK 2, and the activation of NF-κB, preventing the anti-tumoral M1 polarization." (PMID 32192047, 2020). "APM component downregulated by the IFN-γ-phosphorylated STAT1-mediated signaling pathway; results in escaping recognition by tumor antigen-specific cytotoxic T lymphocytes." (PMID 32185135, 2020). "STAT1 and STAT2 are important components of the JAK/STAT pathway, and continued activation of the JAK/STAT signal is associated with tumor progression." (PMID 32685473, 2020). "This will influence the system Xc, resulting in tumor cell ferroptosis via the Janus kinase (JAK) signal transducer and activator of the transcription 1 (STAT1) signaling pathway in tumor cells." (PMID 33298853, 2020). "To investigate the impact of STAT1 isoforms on NK cell functions, we analyzed NK cell-dependent tumor growth control using cell lines that either express an activating receptor ligand (RMA-Rae1) or lack inhibitory receptor ligands (RMA-S)." (PMID 33042133, 2020). "More than that, knocking down USP22 can up-regulate STAT1 to activate JAK1-STAT1-caspase pathway, and promote apoptosis of tumor cell." (PMID 32294625, 2020). "STAT1 signal triggering can also activate T cells to induce apoptosis of PD-L1-sensitive tumor cells." (PMID 32294625, 2020). "The transcription factor signal transducer and activator of transcription 1 (Stat1) is a key effector in tumor immunosurveillance mediated by natural killer (NK)- and T cells." (PMID 32444775, 2020). "Loss of IDO1+ Paneth cells in murine intestinal adenomas with tumor cell-specific Stat1 deletion had profound effects on the intratumoral immune cell composition." (PMID 32444775, 2020). "Patients with Ifit1low CRC benefited from high stromal Stat1 expression immediately after diagnosis, indicating that low expression of tumor cell-intrinsic Stat1-Ido1 sensitizes tumors to immune attack." (PMID 32444775, 2020). "Ifit1 surrogate expression enabled us to discriminate between tumor cell-intrinsic and stromal Stat1-Ido1 functions in bulk gene expression TCGA data." (PMID 32444775, 2020). "These cytokines then lead to paracrine activation of STAT1 and NF-κB pathways in brain metastatic cells, supporting tumor growth and chemoresistance." (PMID 33066331, 2020). "miR-BART20-5p and miR-BART8 target IFN-γ and the signal transducer and activator of transcription 1 (STAT1), respectively, ultimately suppressing cellular immunity against tumor cells." (PMID 32194570, 2020). "In contrast, a study showed that mice with STAT1 deficiency in breast cancer were more likely to have infiltration of PMN-MDSCs and tumor growth, which was rescued by anti-IL-17 treatment." (PMID 32325683, 2020). "Signal transducer and activator of transcription 1 (STAT1) has been reported to act as a tumor suppressor." (PMID 33102485, 2020). "Persistent activation of STAT3/STAT5 often promotes chronic inflammation leading to transformation of healthy cells into malignant cells, while STAT1 suppress tumor growth." (PMID 32991625, 2020). "IHC staining for canonical STAT1 activation detected <3% pY-STAT1+ tumor cells in Stat1flox/floxApcMin tumors." (PMID 32444775, 2020). "We also showed the link between STAT1 overexpression and the increased proliferation of the tumor cells." (PMID 32642677, 2020). "STAT1 is generally considered a tumor suppressor, but growing amounts of evidence suggests tumor-promoting activities." (PMID 32752128, 2020). "Type I and II interferon (IFN) are the major activators of canonical Stat1 signaling, which relies on Tyr701 phosphorylation (pY-STAT1) and mediates tumor suppressive effects of IFN12." (PMID 32444775, 2020). "It is reported that SHP-2 suppresses Th1 immunity in the tumor microenvironment via the PD-1/SHP-2/STAT1/T-bet signaling axis." (PMID 32117720, 2020).
tumor (continued). "Previously, it has been proposed that STAT1 is involved in the regulation of the Warburg effect in the tumor cells by activating a switch from oxidative phosphorylation to anaerobic glycolysis." (PMID 33384992, 2020). "We are the first to show that the two splice isoforms of STAT1 differ in regard to their ability to promote NK cell maturation, cytotoxicity and NK cell-dependent tumor immune surveillance." (PMID 33042133, 2020). "Together with the data from the tumor transplants, this indicates that Stat1β/β mice have a better missing-self recognition than Stat1–/– mice, whereas NKG2D-dependent killing is similarly impaired in Stat1β/β and Stat1–/– mice." (PMID 33042133, 2020). "Additional signaling pathways involved in the anti-tumor immune response were also impaired as STAT1 and STAT3 were also significantly downregulated." (PMID 33034643, 2020). "It has been reported that STAT1 is involved in biological behaviors of cancers, remodeling of the tumor microenvironment, and stemness properties." (PMID 32516753, 2020). "Signal transducer and activator of transcription 1 (STAT1) is a transcription factor that is essential for NK cell maturation and NK cell-dependent tumor surveillance." (PMID 33042133, 2020). "Proteomic analysis of human triple negative breast tumours revealed that Stat1-positive tumours were more aggressive with increased invasion and lymph node metastasis." (PMID 32872349, 2020). "Signal transducer and activator of transcription 1 is an important transcription factor that has repeatedly been shown to be a tumor suppressor." (PMID 33102485, 2020). "Our results would predict that shifts in STAT1 splicing towards a predominant expression of Stat1β would considerably compromise NK cell-dependent tumor surveillance and that this defect cannot be overcome by treatment with exogenous IL-15/IL-15Rα." (PMID 33042133, 2020). "CNOT7 and STAT1 expression levels were determined in tumor and healthy tissues of patients with HCCBC." (PMID 32160402, 2020). "These analyses suggested that tumor cell-intrinsic Stat1-Ido1 expression promotes progression of human CRC, correlates positively with Treg numbers and desensitizes tumors to immune attack." (PMID 32444775, 2020). "CNOT7 expression was significantly higher in tumors than in cirrhotic hepatic tissues, whereas STAT1 was obviously down‐regulated in tumor tissues (both P < 0.01)." (PMID 32160402, 2020). "STAT1 was also found to play an immune-suppressive role in modulating the tumor microenvironment of HNSCC." (PMID 33224866, 2020). "Important evidence also demonstrates the tumor suppressor properties of STAT1 in mammary tumorigenesis." (PMID 32260399, 2020). "Taken together, these data indicate SOCS1 plays a role of tumor suppressor in NPC cells by directing the ubiquitin-proteasome-mediated degradation of STAT1 in the JAK/STAT signaling pathway." (PMID 32831137, 2020). "To assess the capacity of the individual STAT1 isoforms to promote NK cell maturation and anti-tumor activity, we used mice expressing either only STAT1α (Stat1α/α) or only STAT1β (Stat1β/β)." (PMID 33042133, 2020). "Effector T cells can activate STAT1 signaling to upregulate the expression of MHC-I on tumor cells by secreting INF-γ." (PMID 33330629, 2020). "The mRNA levels of most of the correlation-enhancing genes under STAT1 control were upregulated in tumors compared to non-tumor tissues." (PMID 33384992, 2020). "Another study demonstrated that herbal acidic polysaccharide IAPS-2 inhibits the phosphorylation of STAT3 and enhances STAT1 phosphorylation in TAMs from S180 tumor tissues (a syngeneic sarcoma) promoting macrophage polarization toward the M1-like phenotype." (PMID 32486098, 2020). "It is challenging to deduce prognostic information of tumor cell-intrinsic Stat1 and Ido1 expression from CRC TCGA data, because both genes are expressed in neoplastic cells and immune cells." (PMID 32444775, 2020).
tumor (continued). "For instance, signal transducer and activator of transcription 1 (STAT1), a transcriptional factor associated with type I and II interferon signaling, is considered to have anti-tumor activity in the HCC models." (PMID 32411519, 2020). "We found that after silencing of STAT1, the tumor suppression effect of Fra-1 overexpression disappeared through a series of in vivo and in vitro experiments." (PMID 33102485, 2020). "This indicates that loss of IDO1+ Paneth cells and corresponding immunological consequences surpassed tumor-promoting effects of Stat1 deletion in Stat1∆IECApcMin tumors." (PMID 32444775, 2020). "STAT1 is known to be immunomodulatory and is associated with PD-L1, indicating a potential effect of CDK19 on tumor immune microenvironment." (PMID 32752128, 2020). "We then performed statistical analyses to compare STAT1 expression with various clinicopathological features, including patient age and genders, tumor differentiation and location, and MSI/MSS subtype." (PMID 32275681, 2020). "Among the 614 cases of early stage cancer, high levels of cytoplasmic STAT1 expression were positively correlated with older age, poor tumor differentiation, right-sided location, and MSI subtype." (PMID 32275681, 2020). "The tumor suppressor role of miR-29 is mediated by the activation of JAK/STAT1 signaling that further plays a role in MYC-B7-H3 downregulation in MB." (PMID 31382461, 2019). "Remarkably, we found that STAT1 was predominantly present as u-STAT1 form and was highly expressed in the cytoplasm of tumor cells from HCC patients." (PMID 30456450, 2019). "This IFN/STAT1 pathway exerts an antiviral and antitumor activity by inducing cell cycle arrest or apoptosis, whereas it is also involved in tumor progression." (PMID 30709063, 2019). "As a result the STAT1 and NF-kappaB pathways were activated in tumor cells thereby facilitating tumor growth and chemotherapy resistance." (PMID 31226836, 2019). "In general, STAT1 is considered a tumor suppressor, although there is also increasing evidence for tumor promoting functions of STAT1." (PMID 31242951, 2019). "As the key component of IFN signaling, STAT1 have been reported with both pro- and anti-tumor functions during cancer development from clinical studies in cancer patients." (PMID 30456450, 2019). "STAT1 is best known for its tumor suppressive activity in cancer but some tumor-promoting effects have also been documented." (PMID 31752278, 2019). "Although the function of STAT1 was considered to depend on the tyrosine phosphorylation, Stat1-Y701F expressing NK cells are more cytotoxic against tumor cells than Stat1−/− NK cells." (PMID 31781102, 2019). "ISGs of the IRDS members that are known to promote tumor growth and metastasis are regulated by u-STAT1." (PMID 30456450, 2019). "STAT1 carries tumor suppressor functions and regulates various cellular activities, such as apoptosis, angiogenesis, invasion and evasion of the immune system." (PMID 30641486, 2019). "IFN-g secreted by tumor-reactive T cells, signaling through the transcription factor STAT1, is the single major cytokine that induces PD-L1 protein expression." (PMID 31730010, 2019). "On one hand, STAT1 is recognized as a tumor suppressor which can inhibit tumor growth through regulating cell proliferation, differentiation, and death." (PMID 30456450, 2019). "This prompted us to determine the proficiency of the several components of IFNy-STAT1 signaling pathway of tumor cells under nutrient limiting conditions." (PMID 31196219, 2019). "STAT family members notably STAT3 and STAT5 have been involved in cancer progression whereas STAT1 plays opposite role by suppressing tumor growth." (PMID 30847297, 2019). "For example, the expression of transcription factor STAT1 which modulate the cholesterol metabolism and arachidonic acid pathway, was correlated with several types of immune cells in the tumor immune microenvironment." (PMID 31074374, 2019).